BRCA1 (BRCA1 DNA repair associated)
Diseases named in the same sentence as BRCA1 in open-access papers (continued):
Sharing a sentence is not in itself a finding about the gene and the disease.
prostate carcinoma (continued). "A meta-analysis by Lukashchuk and colleagues found that advanced, metastatic prostate cancers show significantly increased rates of mutation in homologous recombination repair enzymes, including BRCA1/2, than primary prostate cancers." (PMID 39095874, 2024). "Several inherited mutations (e.g., BRCA1 and BRCA2) are associated with varying degrees of increased predisposition to prostate cancer." (PMID 37202470, 2024). "Prostate cancer reports also had a relatively high frequency of inactivating alterations in BRCA1/2 (10.1%) or other homologous recombination repair genes (18.3%)." (PMID 37682776, 2024). "Several studies have demonstrated the clinical benefits of PARP inhibitors for these patients, and the US FDA has approved their use for breast, ovarian, and prostate cancer patients with PALB2 or BRCA1 mutations." (PMID 38672648, 2024). "A pivotal role in prostate cancer biology is played by the tumor suppressors BRCA1 and BRCA2, belonging to the homologous recombination deficiency (HRD) repair system, that enables the error-free recovery of double strand breaks (DSBs)." (PMID 39335746, 2024). "This study aims to contribute real-world data on the prevalence of BRCA1/2 and HRR gene mutations in prostate cancer." (PMID 39172235, 2024). "Of the 346 cases, somatic pathogenic mutations in one of the BRCA1/2 genes were identified in 97 cases, which represents 28% of all tumours tested, predominantly HGSOC, breast and prostate cancer." (PMID 38881341, 2024). "This study seeks to contribute real-world data on the prevalence of BRCA1/2 and HRR gene mutations in prostate cancer." (PMID 39172235, 2024). "In our study, the mean age of male carriers was 28 years, and only one male carrier (6.7%) among the fifteen unaffected male BRCA1/2 carriers was above 40, which is the age recommended for prostate cancer surveillance in the guidelines." (PMID 39590130, 2024). "BRCA gene mutations (especially BRCA1 and BRCA2 genes) are primarily involved in breast and gynecological cancers but are also a risk factor for pancreatic or prostate cancers." (PMID 39594177, 2024). "PARPi selectively kill cancer cells with homologous recombination repair deficiency (HRD), as a result, PARPi are widely employed to treated BRCA1/2-mutant ovarian, breast, pancreatic and prostate cancers." (PMID 39318358, 2024). "The effectiveness of PARPi therapies for resistant prostate cancer with alterations in DNA-repair genes, in particular BRCA1 and BRCA2, has been widely tested." (PMID 39335746, 2024). "But due to their detection ratios, P/LP variants in BRCA1/2 and other homologue recombination repair genes represent an important indication for PARP inhibitor therapy in breast, ovarian, pancreatic, and prostate cancer." (PMID 39684258, 2024). "Other unlisted high-scoring genes, such as BRCA1 and BRCA2, have been confirmed to be involved in DNA repair and are also linked to prostate cancer." (PMID 38530778, 2024). "Future studies should also assess the potential implications of BRCA1 epimutations as predictive for PARP-inhibition in other tumor types, in which BRCA1/2 mutations are observed (e.g., prostate cancer)." (PMID 40225940, 2024). "This study offers valuable real-world insights into the landscape of BRCA1/2 and HRR gene mutations and the practical clinical management of HRR gene testing in prostate cancer, contributing to a better understanding of patient eligibility for PARPi treatment." (PMID 39172235, 2024). "Our findings strongly advocate for somatic and germline testing including BRCA1/2 in the evaluation of prostate cancer, especially in cases of metastasis at presentation and a Gleason grade group 5 disease, even if their PSA is lower than 100 ng/mL." (PMID 37568814, 2023).
prostate carcinoma (continued). "By associating MuAt features with driver events identified in PCAWG, MuAt highlighted prostate cancers driven by SPOP mutations, characterized by a 2.3-fold increase in somatic SV burden, exceeding the relative burden in tumours with BRCA1 and BRCA2 mutations." (PMID 37420249, 2023). "BRCA1 and PALB2 genetic aberrations are associated with both breast and prostate cancer predisposition." (PMID 38131903, 2023). "To date, the FDA has approved the use of rucaparib in patients with prostate cancer with BRCA1/2 alterations who have received prior ARSI therapy and taxane-based chemotherapy." (PMID 37168382, 2023). "Here, using a genome-wide CRISPR-Cas9 knockout screen, the authors identify MMS22L as a biomarker for sensitivity to PARP inhibition in BRCA1/2-proficient prostate cancer." (PMID 36650183, 2023). "Regarding BRCA1 affected by compound 6, it has been seen that BRCA1 and BRCA2 pathogenic variants are associated with prostate cancer risk." (PMID 37511023, 2023). "The presence of a pathogenic or deleterious mutations in BRCA1 or BRCA2 is associated with a greater risk of developing breast, ovarian, pancreatic, and prostate cancers but are also predictive to response to olaparib." (PMID 37907567, 2023). "Recent oncology guidelines recommend BRCA1/2 testing for a wide range of prostate cancer (PCa) patients." (PMID 36509931, 2023). "When repeating analyses for pathogenic variants in four additional genes (BRCA1, RAD50, MLH1, and MSH6) with weaker evidence of association with prostate cancer risk, the risk modifying effect of PRS was similar, albeit the associations were diminished." (PMID 38014910, 2023). "Mutations in breast cancer gene 1 (BRCA1) and breast cancer gene 2 (BRCA2) have been associated with male breast cancer (MBC), as well as prostate cancer (PCa)." (PMID 38161833, 2023). "Further, inhibition of BET proteins also led to attenuation of RAD51 and BRCA1 proteins in breast, ovarian, and prostate cancer models." (PMID 37370140, 2023). "Lucaparib maintenance therapy is an excellent treatment for patients with platinum-sensitive advanced pancreatic cancer with BRCA1/2 or PALB2 pathogenic variants, primarily in ovarian and prostate cancers." (PMID 37834477, 2023). "PARP inhibitors have been established based on the concept of synthetic lethality in BRCA1/2 mutant cancer cells, and they represent a great breakthrough in precision medicine for prostate cancer treatment." (PMID 37174127, 2023). "Olaparib (Lynparza®) is the first drug based on gene mutations, especially BRCA1 and BRCA2 pathogenic mutations, for the treatment of advanced prostate cancer and was highly expected to mark the dawn of personalized medicine in this field." (PMID 37174127, 2023). "Mutations in BRCA1 and BRCA2 are known to be associated with an increased risk of prostate cancer in men." (PMID 36998466, 2023). "Mutations of BRCA1 and BRCA2 were well known as a risk factor for hereditary breast cancer and there were significantly increased risks of melanoma and prostate cancer in BRCA mutation carriers." (PMID 35932099, 2022). "Both cancers are also associated with pathogenic variants in male BC susceptibility genes: prostate cancer with the BRCA1/2 and CHEK2 genes and stomach cancer with the BRCA1/2 and CHEK2 genes." (PMID 36115878, 2022). "On the other hand, the first major biomarker study in prostate cancer (PCa) (the PROfound study) reported that 17.6% of the 4425 patients had mutations in at least one of the predefined 15 HRR genes, which included BRCA1, BRCA2, and ATM." (PMID 35055413, 2022). "The incidence of BRCA1/2 alterations in prostate cancer are evenly split across somatic and germline alterations." (PMID 36497408, 2022). "Carriers of a pathogenic germline variant (PV) in BRCA1 or BRCA2 are at increased risk for a number of malignancies, including breast, ovarian, pancreatic, and prostate cancer." (PMID 36497436, 2022).
prostate carcinoma (continued). "Both the HRD-DNA model and the HRD-RNA model captured biallelic loss of BRCA1/2 with high sensitivity and specificity in BRCA-associated tumors (breast, ovarian, pancreatic, and prostate cancer)." (PMID 35643464, 2022). "Male BRCA1 and BRCA2 carriers are likely to benefit from more personalized breast and prostate cancer risk estimates." (PMID 34320204, 2022). "BRCA1/2 homozygous deletions are infrequent except in prostate cancer, where BRCA2 deletions have been reported at 2.6% frequency and accounted for 25% of BRCA1/2-altered cases." (PMID 35740616, 2022). "In the case of ovarian and prostate cancers, their classification as homologous recombination repair (HRR) deficient (HRD) or mutated also makes PARPi an available treatment option beyond BRCA1 or BRCA2 mutational status." (PMID 36969741, 2022). "BRCA1/2 and ATM aberrations have been reported to be associated with a more aggressive prostate cancer phenotype, with an increased risk of disease recurrence and poorer survival outcomes." (PMID 35740343, 2022). "Germline BRCA1 and BRCA2 pathogenic variant carriers are recognized to be at increased risk for multiple cancers including breast, ovarian, pancreatic, and prostate cancer, with risk management recommendations for these cancers included in BRCA1/2 guidelines." (PMID 36497436, 2022). "BRCA2 (12–18%), ATM (3–6%), CHEK2 (2–5%), and BRCA1 (< 2%) are the most commonly affected HRR genes in prostate cancer." (PMID 35159068, 2022). "BRCA1 was expressed at relatively high levels in prostate cancer compared with a low BRCA1 immunostaining in normal prostate epithelium." (PMID 35432218, 2022). "We identified ancestry-linked germline and somatic mutation frequencies in DNA damage repair genes (BRCA1, BRCA2, APC, and ATM), as well as three novel prostate cancer–associated genes (CACNA2D2, SYNE1, and ADAMTS2)." (PMID 36922933, 2022). "Germline mutations in BRCA1 and BRCA2 have been associated with an increased incidence of prostate cancer." (PMID 36551924, 2022). "BRCA2 variants were the most prevalent at 5.3%, and variants in ATM, CHEK2, PALB2, BRCA1, and RAD51D were also more common among men with lethal prostate cancer." (PMID 36446039, 2022). "The frequencies of mutations in ATM and BRCA1 and BRCA2 were compared in 313 men who died of prostate cancer and 486 men with localized prostate cancer." (PMID 35732815, 2022). "The use of PARPi in cancer therapy is an effective targeted approach in ovarian, breast, pancreatic, and prostate cancer subtypes with defective BRCA1/2 genes, commonly identified as having the “BRCAness phenotype”." (PMID 36612003, 2022). "Less OS data were reported for other tumors: 6 studies for BRCA2m compared with BRCA2 wt in prostate cancer with an HR of 1.9 (1.1–3.2) and 2 studies for BRCA1/2m compared with BRCA1/2 wt in pancreatic cancer with an HR of 1.5 (0.8–3.1)." (PMID 35909902, 2022). "For BRCA1 and BRCA2, breast and pancreatic cancer showed a ratio of 2:1 for germline versus somatic mutations; in ovarian and prostate cancer the ratio was 1:1, while in bladder and lung cancer, mutations were mostly of somatic origin." (PMID 34979999, 2022). "The prevalence of BRCA1 and BRCA2 pathogenic variants was 0.38% and 4.30%, respectively, in prostate cancer patients." (PMID 36439508, 2022). "Among 743 Black prostate cancer patients, we identified 26 unique pathogenic (P) or likely pathogenic (LP) variants in 14 genes (including HOXB13, BRCA1/2, BRIP1, ATM, CHEK2, and PALB2) among 30 men, or approximately 4.0% of the patient population." (PMID 36446039, 2022). "Apart from the EOC, mutations in the DDR genes, such as BRCA1 and BRCA2, are common in prostate cancer as well." (PMID 36010882, 2022). "Yadav and colleagues observed increased somatic mutations of BRCA2, BRCA1, and ATM in AA prostate cancer." (PMID 36922933, 2022).
prostate carcinoma (continued). "BRCA1 and BRCA2 pathogenic variants (PVs) are associated with prostate cancer (PCa) risk, but a wide range of relative risks (RRs) has been reported." (PMID 34963702, 2022). "For example, most hereditary cancer panels include genes for breast, ovarian and colon cancer – and includes the five main genes for prostate cancer discussed here (BRCA1, BRCA2, CHEK2, ATM, PALB2)." (PMID 35732815, 2022). "The incidence of prostate cancer is greater among BRCA mutation carriers; namely, 1.35-fold and 2.64-fold greater in BRCA1 and BRCA2 carriers, respectively." (PMID 36010882, 2022). "BRCA1 and BRCA2 mutations are associated with an increased risk of developing numerous cancers, including breast, ovarian, pancreatic, melanoma and prostate cancer." (PMID 35303741, 2022). "Deleterious mutations of BRCA1 and BRCA2 are associated with increased risk of prostate cancer and experienced very aggressive course of the disease." (PMID 35785170, 2022). "The Philadelphia Prostate Cancer Consensus Conference guidelines 2019 state that men with metastatic PCa should have germline testing in BRC2/BRCA1, DNA MMR genes (recommended) while ATM gene testing should be considered." (PMID 34830851, 2021). "Studies have demonstrated that men with Prostate Cancer (PCa) harboring BRCA2/BRCA1 genetic aberrations, are more likely to have worse disease and a poorer prognosis." (PMID 34830851, 2021). "Prostate cancer diagnosis was also earlier in BRCA2 carriers at 52 years compared to BRCA1 carriers at 58 years." (PMID 34575694, 2021). "Prostate cancer was also diagnosed earlier in this cohort (BRCA1: 58 y vs. BRCA2: 52 years) as compared to the general population at 67 years." (PMID 34575694, 2021). "A large study on 2019 patients with prostate cancer showed that BRCA1/2 status is an independent prognostic value for OS (HR 1.9; 95% CI 1.1–3.3; p = 0.012)." (PMID 34439347, 2021). "At the same time, treatment of prostate cancer cells with the EZH2 inhibitor DZNep abrogated BRCA1-dependent regulation of CSC phenotypes." (PMID 34638302, 2021). "For example, the prostate cancer risk by age 80 years at the 5th and 95th percentiles of the PRS varies from 7% to 26% for carriers of BRCA1 PVs and from 19% to 61% for carriers of BRCA2 PVs, respectively." (PMID 34298749, 2021). "For example, PARP inhibitors were FDA approved in prostate cancer with BRCA1/2 alterations and other homologous recombinational repair (HRR) genes such as ATM." (PMID 34200508, 2021). "Many BRCA1 and BRCA2 LGRs have been associated with hereditary breast, ovarian and prostate cancers." (PMID 34242281, 2021). "Genetic testing, particularly for BRCA1/2, is increasingly important in prostate cancer (PCa) care, with impact on PCa management and hereditary cancer risk." (PMID 34542414, 2021). "On the other hand, the risk of developing male breast cancer, prostate cancer, pancreatic cancer, and melanoma in BRCA2 mutation carriers has been reported to be higher than in BRCA1." (PMID 34356066, 2021). "BRCA1 coregulates the androgen receptor (AR) which mediates a signalling pathway crucial in developing prostate cancer." (PMID 34884434, 2021). "Olaparib is inhibiting PARP1, PARP2, and PARP3 and is used as a therapy for cancer in people with hereditary BRCA1 or BRCA2 mutations, which include some ovarian, breast and prostate cancers." (PMID 33481867, 2021). "Germline mutations in BRCA1 and BRCA2 genes have been associated with a high risk of ovarian/breast and prostate cancers." (PMID 34242281, 2021). "The Belgian Society of Human Genetics recommends annual prostate cancer screening with serum PSA and DRE for male BRCA1 and BRCA2 mutation carriers from the age of 40 onwards." (PMID 32655641, 2020).
prostate carcinoma (continued). "Prostate cancer screening in BRCA2 mutation carriers is recommended starting at the age of 40, whereas in BRCA1 mutation, carriers screening should be considered from the age of 40 onwards." (PMID 32655641, 2020). "Knockdown of SPOP or expression of prostate cancer-associated SPOP mutants sensitized prostate cancer cells to PARP inhibitor, olaparib, as was seen in BRCA1-depleted cells." (PMID 33023230, 2020). "The results demonstrated that 65% of patients diagnoses with a BRCA1/2-mutated prostate carcinoma, and 31% of patients with alternative DDR gene mutated prostate cancers, achieved a composite response." (PMID 33015058, 2020). "In detail, 6 women had a first-degree relative, 13 women (two of which BRCA1 carriers) had a second-degree relative, while 3 women (one BRCA1 carrier) presented two first or second-degree relatives affected by prostate cancers." (PMID 32429297, 2020). "Mutations in DNA repair genes such as BRCA1, BRCA2, ATM, CHEK2, and PALB2 are of importance in prostate cancer." (PMID 32197306, 2020). "Germline mutations in the transcription factor HOXB13 and DNA damage repair genes such as BRCA1, BRCA2, CHEK2, as well as the mismatch repair (MMR) genes MSH6 and PMS2, have been shown to increase the risk of prostate cancer, the most common cancer among men." (PMID 32197306, 2020). "Deleterious mutations in the tumour suppressor genes BRCA1 and BRCA2 are associated with high risks of breast and ovarian cancer, and have been implicated in the genetic susceptibility to prostate cancer (PCa)." (PMID 31495749, 2020). "The prime example is using poly (ADP-ribose) polymerase (PARP) inhibitors for the treatment of adults with advanced breast, ovarian, and prostate cancers in the context of germline mutations in DDR genes, such as BRCA1, BRCA2, ATM, or PALB235–37." (PMID 32371905, 2020). "BRCA1 and BRCA2 mutations have been associated with prostate cancer (PCa) risk but a wide range of risk estimates have been reported that are based on retrospective studies." (PMID 31495749, 2020). "Men with BRCA1/2 PV/LPVs should undergo clinical breast examination every 6–12 months, starting at the age of 35, and annual prostate cancer screening, starting at the age of 40 (in particular in BRCA2 PV/LPV carriers)." (PMID 32046255, 2020). "Germline mutations in BRCA2 have been linked to a higher risk of prostate cancer (PCa), and high frequency of BRCA1 and BRCA2 (BRCA1/2) gene alterations was recently reported in metastatic castration-resistant PCa specimens." (PMID 30542053, 2019). "Inhibition of EZH2 and BRCA1 in experimental models of prostate cancer induces an increase of cancer stem cell properties." (PMID 31366128, 2019). "An example of such a phenotype is a patient with a pathogenic variant in the gene BRCA1 [Online Mendelian Inheritance in Man (OMIM) gene #113705]8, which is associated with increased risk of developing breast, ovarian, and prostate cancers." (PMID 31737042, 2019). "Poly ADP-ribose polymerase (PARP) inhibitors and platinum-based chemotherapy have proven to be effective in the treatment of other tumor types linked to BRCA1 and BRCA2 alterations and several trials are currently evaluating their efficacy in prostate cancer." (PMID 30871108, 2019). "Defects in DNA damage repair caused by mutations in BRCA1/2, ATM or other genes have been shown to play an important role in the development and progression of prostate cancer." (PMID 31549213, 2019). "The presence of prostate cancer was significantly higher in BRCA2 compared to BRCA1 patients or wild type patients (p < 0.05)." (PMID 29884136, 2018). "In advanced prostate cancer, recently reported BRCA mutation rates, assessed by whole genome sequencing, were 0.6% for BRCA1 and 12% for BRCA2; in all cases biallelic inactivation was present." (PMID 30518089, 2018).